FTO (FTO alpha-ketoglutarate dependent dioxygenase)
Diseases named in the same sentence as FTO in open-access papers (continued):
Sharing a sentence is not in itself a finding about the gene and the disease.
tumor (496 papers, 2011 to 2026). "Dysregulation of FTO has been implicated in various cancers as either a tumour suppressor or an oncogene, depending on the cellular context." (PMID 40621649, 2025). "Consistent with prior studies in other tumor cells, FTO loss led to a noticeable increase in m6A abundance." (PMID 40435251, 2025). "The results confirmed that FTO expression was significantly higher in tumour tissues compared with adjacent non‐tumour tissues and additionally revealed that FTO expression was positively associated with advancing TNM stage and with tumour volume (r = .3891)." (PMID 40621649, 2025). "FTO-mediated demethylation of key transcripts (e.g., PD-L1 mRNA) has been implicated in tumor immune evasion and resistance to anti-PD-1 therapy." (PMID 41280938, 2025). "A growing body of evidence suggests that demethylases, including ALKBH5 and FTO, are linked to the survival of cancer patients and the infiltration of immune cells within tumor tissues." (PMID 39987091, 2025). "created a nanoparticle platform that releases tumor‐associated antigens and FTO inhibitors to dendritic cells (DCs)." (PMID 39802639, 2025). "Loss of FTO increased global m6A methylation, promoting tumor cell proliferation, migration, and invasion, whereas FTO overexpression reversed these effects both in vitro and in vivo." (PMID 41141648, 2025). "Mechanistically, FTO modulated m6A methylation–dependent regulation of proliferation‐associated proteins such as Ki67, thereby suppressing tumor growth in xenograft models." (PMID 41141648, 2025). "In contrast, elevated expression of FTO in PDAC is linked to a worse prognosis, and silencing FTO halts tumor cell growth." (PMID 40271153, 2025). "Recent research has also revealed that RNA methylation regulated by the fat mass and obesity-associated protein (FTO) gene plays a crucial role in tumor cell proliferation, migration, and invasion." (PMID 40282437, 2025). "Firstly, we showed that GC tissues and cells dramatically increased FTO, which was associated with advanced nerve invasion, tumor size, and LNM, as well as a poor prognosis." (PMID 38956367, 2024). "Fat mass and obesity‐associated protein (FTO) is the first identified m6A demethylase, and its imbalanced expression is critical in the development and progression of several tumours, including TC, renal cancer, breast cancer and bladder cancer." (PMID 39163517, 2024). "A total of 5 studies reported the association between FTO expression levels and tumor differentiation (poorly differentiated vs moderately to well-differentiated) in gastric cancer patients." (PMID 39331892, 2024). "The upregulation of FTO is associated with advanced nerve invasion, tumor size, and LNM, as well as the poor prognosis in GC patients, and promoted GC cell viability, colony formation, migration and invasion." (PMID 38956367, 2024). "Increased FTO expression has been associated with a larger tumor size, a higher TNM stage and grade, and a shorter survival time in OSCC patients." (PMID 36582218, 2023). "FTO downregulation was linked to tumor size, metastasis, and vascular invasion, which predicted impaired prognosis." (PMID 36718644, 2023). "FTO contributes to the loss of the von Hippel-Lindau (VHL) tumour suppressor in clear cell renal cell carcinoma (ccRCC)." (PMID 36859310, 2023). "The results indicated that FTO levels were significantly associated with tumor TNM stage (P = .001), tumor size (P = .009) and lymph node metastasis (P = .002)." (PMID 37861518, 2023). "The purpose of this study was to investigate the role of m6A demethylase fat mass and obesity-associated protein (FTO) in the tumor metastasis of non-small cell lung cancer (NSCLC)." (PMID 37919739, 2023). "Another m6A demethylase, FTO, has also been found to be associated with tumor cell escape from immune surveillance through its effect on glycolytic metabolism." (PMID 37485079, 2023).
tumor (continued). "Recently, a study reported that loss of FTO inhibited tumor growth and blocked FTO-mediated immune evasion by enhancing CD8+ T cell infiltration in tumors." (PMID 36960074, 2023). "This study aimed to explore the role of the m6A demethylase fat mass and obesity-associated protein (FTO) in the tumor metastasis of NSCLC." (PMID 37919739, 2023). "FTO mainly played a tumor-suppressive role via reducing metastasis-associated protein 1 (MTA1) expression in an m6A-dependent manner." (PMID 35945194, 2022). "Meanwhile, fat mass and obesity-associated protein (FTO) has the potential to affect the regulation of m6A modification in the mRNA of key oncogenes as well as tumor suppressor genes that facilitate tumor progression." (PMID 35721711, 2022). "In vivo analysis showed that sh-APOE significantly impaired tumor growth and tumor weight in xenograft mouse models caused by sh-FTO." (PMID 35090515, 2022). "Unlike other tumors, emerging evidence has demonstrated that FTO is associated with inhibition of tumor progression in GC." (PMID 34399770, 2021). "Here we report that m6A demethylation of LncRNA LINC00022 by fat mass and obesity-associated protein (FTO) promotes tumor growth of ESCC in vivo." (PMID 34544449, 2021). "Mechanistically, FTO exerted a tumor suppressive role by inhibiting metastasis-associated protein 1 (MTA1) expression in an m6A-dependent manner." (PMID 34218271, 2021). "In this study, we first demonstrated that FTO expression was downregulated in CRC tumor tissue and that higher FTO expression was associated with better prognosis in CRC patients." (PMID 34218271, 2021). "As expected, loss of FTO significantly compromised xenograft tumor growth in nude mice compared to the control group." (PMID 33461172, 2021). "The demethylase FTO (fat mass-and obesity-associated protein) decreases global m6A levels, leading to either downregulation of tumor suppressor genes or upregulation of tumor promoter genes." (PMID 31735169, 2019). "The Von Hippel‐Lindau‐deficient cells expressing FTO restores mitochondrial activity, induces oxidative stress and ROS production and shows impaired tumour growth, through increasing expression of PGC‐1α by reducing m6A levels in its mRNA transcripts." (PMID 30648791, 2019). "And the expression level of FTO is associated with T stage and tumor size (p < 0.05)." (PMID 37605223, 2023). "Then, after the co-transfection of FTO plasmids and miR-4739 mimics into HepG2 and Hep3B cells for 48 h, we found that ectopic expression of FTO prevented the cell proliferation, colony formation, and cell invasion, and reversed tumor-promoting effects caused by miR-4739." (PMID 35858900, 2022). "Taken together, these data suggested that FTO was significantly involved in GC, especially in tumor liver metastasis, and it might be associated with metastatic progression of GC." (PMID 35064107, 2022). "In addition, upregulation of FTO has been linked with glioblastoma stem cell self-renewal pluripotency and tumor growth." (PMID 36497402, 2022). "Both up-or down-regulated FTO has been implicated in carcinogenesis and tumor progression." (PMID 35311620, 2022). "More recent studies have linked increased expression of FTO to other tumours." (PMID 33461542, 2021). "More importantly, by doing plentiful in vitro experiments, we demonstrated that lncRNA AC026691.1 could function as a tumor suppressor gene in GC, which has an intimate association with m6A eraser, namely fat mass and obesity-associated protein (FTO) gene." (PMID 34399770, 2021). "Thus, beyond the demethylating function, the ALK family and FTO were shown to have a broader biological function, being also implicated in tumor chemoresistance." (PMID 34683137, 2021).
tumor (continued). "To figure out the mechanism underlying the tumor-suppressive effect of FTO expression on BCa cells, we detected the expressions of the known differentially m6A methylated genes, including MALAT1, CSNK2A2, ITGA6, and NOTCH1, which were found to correlate with BCa progression in previous studies." (PMID 34499008, 2021). "Similarly, FTO was shown to induce GSCs growth, self-renewal, tumour progression, and was associated with poor survival through regulation of ADAM19." (PMID 33461542, 2021). "Loss of FTO in ICC is associated with tumor aggressiveness and poor prognosis." (PMID 33372610, 2020). "Moreover, the decrease in ALKBH5 and FTO mRNA levels was associated with a decrease in total and tumor-specific survival times after nephrectomy." (PMID 32398132, 2020). "A better understanding of the role of FTO (or m6A) in variant tumour types and at different stages of tumorigenesis will be significant in testing whether this pathway will be useful to therapeutic intervention." (PMID 30648791, 2019). "Collectively, these results indicate that the FTO expression is frequently down‐regulated in ccRCC and associated with poor prognosis, suggesting that FTO may function as a tumour suppressor in ccRCC development." (PMID 30648791, 2019). "Moreover, suppression of FTO causes tumor regression and promotes survival rates in GSC-grafted mice." (PMID 29439529, 2018). "Furthermore, the roles and the underlying mechanism of FTO as well as m6A modification in tumor progression, which might provide new ideas for antitumor therapy, deserve further investigation." (PMID 40712780, 2025). "Therefore, the potential use of FTO inhibitors, in addition to anti-tumor and weight loss, may also be developed as drugs for neurological diseases." (PMID 36118041, 2022). "Therefore, FTO inhibitors may also be developed as drugs for neurological diseases, besides their anti‐cancer and weight‐reducing effects in addition to anti‐tumour and weight loss, may also be developed as drugs for neurological diseases." (PMID 33029866, 2020). "Our study reveals the regulatory role of circGDI2 in driving HCC glycolysis and tumor growth, and the involvement of m6A modification mediated by FTO." (PMID 41439029, 2026). "Consistently, in xenograft models, FTO promoted tumor growth and ibrutinib resistance in a manner partly dependent on Myc." (PMID 41527993, 2026). "Functional assays showed that FTO knockout or knockdown suppressed cell proliferation and colony formation, whereas FTO overexpression promoted tumor growth and increased ibrutinib half-maximal inhibitory concentration." (PMID 41527993, 2026). "FTO not only promotes cell proliferation but also supports tumor metastasis by affecting cell migration and invasion." (PMID 39802639, 2025). "FTO acts as a tumor suppressor by negatively regulating VEGFA expression, highlighting its potential as a therapeutic target for HCC treatment." (PMID 40316995, 2025). "Silencing FTO results in decreased expression of these targets, thereby suppressing tumor progression." (PMID 41141648, 2025). "Studies revealed FTO’s significant role and potential mechanism in prohibiting tumor stem cell self-renewal and immune evasion." (PMID 40823087, 2025). "Huang etal.‘s research in cervical carcinogenesis proved that FTO accelerates tumor progression by eliminating m6A methylation from Bone Morphogenetic Protein 4 (BMP4) mRNA." (PMID 39904996, 2025). "In our study, we further determined that FTO mRNA expression was elevated in tumor tissues in HNSC from the TCGA database." (PMID 40712780, 2025). "Second, we primarily focused on LUAD, and the relevance of the FTO–IGFBP3 axis to other tumour types remains to be explored." (PMID 40621649, 2025). "In the present study, we found that FTO overexpression enhanced the ferroptosis resistance, while FTO silencing or inhibition induced obvious ferroptosis of tumor cells." (PMID 40712780, 2025).
tumor (continued). "To validate the tumor-suppressive role of FTO in vivo, we established a subcutaneous xenograft model using U251 cells with stable FTO overexpression (oeFTO) or knockdown (shFTO-1)." (PMID 40970086, 2025). "A Kaplan–Meier survival analysis of NSCLC tumor tissues showed that those with low FTO expression had a longer median survival time than those with higher expression." (PMID 40722726, 2025). "FTO acts as a tumor suppressor in PTC by downregulating the cystine/glutamate antiporter solute carrier family 7 member 11 (SLC7A11) via the ferroptosis pathway." (PMID 39802639, 2025). "Conversely, overexpression of FTO in vitro and in vivo significantly inhibited these tumorigenic phenotypes and suppressed tumor growth in a mouse xenograft model." (PMID 41141648, 2025). "It was observed that the knockout of FTO significantly enhanced tumor formation within the orthotopic liver microenvironment and strengthened lung metastasis in nude mice." (PMID 40316995, 2025). "Silencing of FTO has been shown to enhance cell motility, invasion, and tumor growth across various epithelial cancers." (PMID 40271153, 2025). "The in vivo data confirmed our in vitro results, with IGFBP3‐oe reversing the inhibition of tumour growth observed in FTO‐kd cells." (PMID 40621649, 2025). "Analogs of α-ketoglutarate (α-KG) represent another class of FTO inhibitors with potential application as anti-tumor drugs; these compounds compete with α-KG by chelating iron within the FTO active site, thereby inhibiting its catalytic function." (PMID 40994448, 2025). "To investigate the role of FTO in pNENs, we first analyzed its expression in tumor and adjacent normal tissues using immunohistochemistry." (PMID 39990672, 2025). "MA2 inhibits FTO activity, thereby disrupting this oncogenic feedback loop and exerting anti-tumor effects." (PMID 40823087, 2025). "In vivo experiments further confirmed that FTO overexpression markedly suppressed tumor initiation and growth in mouse models." (PMID 41141648, 2025). "RNA-Seq analysis identified VEGFA as a key gene downregulated by FTO, implicating its role in angiogenesis and tumor progression." (PMID 40316995, 2025). "To directly test the tumor-suppressive function of FTO, we generated U251 and U87MG cell lines stably overexpressing FTO (oeFTO)." (PMID 40970086, 2025). "The in vivo model confirmed that FTO overexpression suppressed tumor growth, while its knockdown accelerated it." (PMID 40970086, 2025). "Mechanistic studies demonstrated that FTO is localized in both the nucleus and cytoplasm and that its tumor‐suppressive effects are mediated, at least in part, through modulation of Ki67 expression." (PMID 41141648, 2025). "Our immunohistochemistry study found significantly higher FTO expression in the nucleus of the late-stage tumor tissues compared to the early-stage tumor tissues." (PMID 40722726, 2025). "Overall, these findings elucidate that FTO silencing amplifies tumor invasion and metastasis in HCC." (PMID 40316995, 2025). "FTO exerts oncogenic effects on various types of cancer cells, promoting tumor cell growth by activating survival and cell-cycle signaling, such as PI3K/Akt/mTOR pathway, MYC, β-catenin, and CEBPA." (PMID 40234389, 2025). "To summarize, FTO plays a pro-cancer role in various tumors, and its high expression can affect the malignant biological behavior of tumor cells." (PMID 39820532, 2025). "Conversely, FTO has been shown to act as a tumor suppressor, and its expression is decreased in PTC." (PMID 40243425, 2025). "Specifically, FTO overexpression can motivate the migration and invasion of tumor cells, suggesting that FTO is a viral oncogene." (PMID 39820532, 2025).
tumor (continued). "These diverse roles underscore FTO's significance as a molecular nexus in cancer biology, with far‐reaching implications for both tumor development and potential therapeutic intervention strategies." (PMID 39802639, 2025). "Translational studies involving organoid models and xenograft tumor models revealed that the use of FTO inhibitors significantly suppressed PDAC growth." (PMID 41184232, 2025). "The target genes of FTO determine its promotive or suppressive effects on tumor progression; therefore, how the MIDN/FTO axis affects tumor progression urgently needs to be investigated in the future." (PMID 40002690, 2025). "Progress has been made in developing small molecule inhibitors targeting FTO, with some inhibitors for anti-inflammatory or anti-tumor purposes already established." (PMID 40427510, 2025). "Demethylation of mML by the erasers, ALKBH5 and FTO, can result in both tumorigenesis and tumor suppression in different cancers." (PMID 40243425, 2025). "Conversely, FTO overexpression significantly reduced m6A methylation in tumor samples compared to the NC‐OE group." (PMID 41141648, 2025). "While the precise mechanism by which FTO influences tumor development remains elusive, mounting evidence suggests a strong correlation between FTO and the incidence, progression, and prognosis of certain malignant neoplasms." (PMID 39820532, 2025). "Conversely, regulators such as IGF2BP2, METTL16, and FTO demonstrated highly context-specific and sparse expression across tumor types." (PMID 40565233, 2025). "We also examined FTO expression in 7 paired GC patient samples, including tumor and adjacent tissues, via Western blotting, revealing elevated expression in GC tissues." (PMID 39773744, 2025). "The downregulation of the FTO/PHF1 axis promotes tumor cell self-renewal, progression, and poor prognosis by enhancing FOXM1 expression, thereby compromising therapeutic efficacy." (PMID 40823093, 2025). "In this study, we demonstrated that FTO was up-regulated in pNENs and played a critical role in tumor growth and lipid metabolism." (PMID 39990672, 2025). "Overexpression of FTO significantly inhibited tumor formation and reduced tumor growth, consistent with previous findings on the anticancer potential of FTO." (PMID 41141648, 2025). "In GC, ALKBH5/FTO was found to be highly expressed in tumor cells and activated Wnt and PI3K-Akt signaling to promote GC development." (PMID 40136363, 2025). "When dividing patients into low and high expression levels, we found that 68.7% of early-stage tissue samples exhibited low expression level, and 55% of late-stage tumor tissues had high FTO expression." (PMID 40722726, 2025). "Pre-clinical studies have shown that FTO inhibitors, such as Rhein and meclofenamic acid (MA), have the potential to inhibit tumor growth." (PMID 40747121, 2025). "Dac51 stabilizes FTO while simultaneously blocking FTO-mediated immune evasion, synergizing with ICIs to enhance anti-tumor efficacy." (PMID 40823087, 2025). "Our findings revealed significant associations between FTO expression and sex (P = 0.026), GGT (P = 0.009), tumor size (P = 0.034), microvascular invasion (P = 0.001), and tumor differentiation (P < 0.001)." (PMID 40316995, 2025). "FTO‐mediated m6A demethylation increases the levels of the transcription factors c‐Jun, JunB, and C/EBPβ in tumor cells, which alters glycolytic metabolism, impairs CD8+ T cell function, and inhibits tumor progression." (PMID 39802639, 2025). "The intricate interplay between tumor-suppressive and tumor-promoting mechanisms underscores the complexity of FTO’s involvement in cancer progression." (PMID 40722726, 2025). "The results indicated that FTO knockdown evidently inhibited pNENs growth, as evidenced by the reduced tumor volume, tumor weight, and immunohistochemical (IHC) staining of ki67." (PMID 39990672, 2025).